APC (APC regulator of Wnt signaling pathway)
Diseases named in the same sentence as APC in open-access papers (continued):
Sharing a sentence is not in itself a finding about the gene and the disease.
cancer (continued). "In hypermutated cancers, APC, TGFBR2, BRAF, MSH3, MSH6, SLC9A9, and TCF7L2 were highly mutated, in particular the frequent mutations of BRAF (V600E)." (PMID 33719345, 2021). "Upon RNAi-mediated downregulation of a tumor suppressor gene APC, the transduced organoids were serially transplanted into mice to allow exposure to in vivo microenvironments, which play relevant roles in cancer development." (PMID 34548081, 2021). "Recent studies have linked the complexity of YAP/TAZ in cancer with other cancer-relevant factors and pathways, such as KRAS, APC, LKB1, aberrant GPCR signaling, and WNT signaling." (PMID 33830081, 2021). "Regarding specific cancer-associated genes, the CYT-high subgroup had more CNAs, including gains in NF1, CDK12, ERBB2, RARA, MDM4 and MYC; and losses in BRCA1, CD274 and APC." (PMID 34316699, 2021). "Taken together, these results suggest that by competitively absorbing miR-346, lncRNA GHRLOS upregulates APC and further regulates cancer cell proliferation, invasion, and apoptosis in NSCLC." (PMID 33968785, 2021). "Here, we will review the APC-Asef interaction in cancer biology, the structural complex of APC-Asef, two generations of peptide inhibitors of APC-Asef, and small molecule inhibitors of APC-Asef, focusing on research articles over the past 30 years." (PMID 33968990, 2021). "Further, combinatory oral administration suppressed in vivo tumorigenesis and the cancer progression of APC-MIN mice models." (PMID 34298652, 2021). "While inactivation of APC in FAP and sporadic CRCs is due to APC mutation, an often-unnoticed fact is that, in other cancers, APC inactivation often results from the hypermethylation of APC’s promoter, and its epigenetic silencing." (PMID 34299349, 2021). "The hypermethylation of APC promoter was found to be prevalent in most gastrointestinal (GI) cancers; it was detected in tumor tissues and even the corresponding serum of cancer patients, whereas it was generally less ubiquitous or absent in non-tumor tissues." (PMID 33968756, 2021). "Under normal conditions, cancer cells turn on the canonical Wnt/β-catenin pathway to disintegrate the destruction complex (Axin, APC, GSK3β, and β-catenin; dash circle) and stabilize β-catenin." (PMID 34069945, 2021). "At stage 3, STARD13, CBFA2T3, RECK, and SASH1 had strong accordant/discordant effects on expression of genes in cancer, while APC, EXT1, NBL, KLK10, and PTCH1 had very weak accordant/discordant impacts on expression of genes in cancer." (PMID 33580150, 2021). "Comparing the mutation status of cancer critical genes in PUMC-CRC1 with that in 19 commonly-used CRC cell lines, it was proved that PUMC-CRC1 with APC (p.T1493fs), KRAS (p.G12V) and SMAD4 (p.V506A) mutations was a unique MSS CRC cell line." (PMID 34162944, 2021). "The regulatory axis of canonical Wnt-dependent Axin2 plays an important role in the regulation of Snail (SNAI1) mediated EMT in cancer, is a typical downstream target of the TCF/LEF transcript factor, and is highly abundant in CRC due to the loss of APC." (PMID 34298652, 2021).
cancer (continued). "Genes such as EGFR, PIK3CA, DROSHA, MDM4, and APC were located inside recurrently aberrant regions, while other known cancer-genes such as NF1, MET and mTOR were identified as cis-genes and located outside the most recurrently altered regions." (PMID 34625038, 2021). "piR-823 increased the expression of DNMTs, promoted DNA methylation of gene adenomatous polyposis coli (APC), thereby activating Wnt signaling and inducing cancer cell stemness in the luminal subtype of breast cancer cells." (PMID 33791297, 2021). "These stem-like cells have been shown to co-localize with APC in their stromal niche, suggesting that their interactions are more impacted by cross-presentation than by direct presentation by cancer cells." (PMID 33968757, 2021). "In contrast, APC1638T mice had a preserved β-catenin binding site in the center of the APC molecule, so cell proliferation via Wnt signaling can be blocked and thereby prevent cancer in APC1638T mice." (PMID 34948207, 2021). "In conclusion, in the incipient SNADETs, such as small lesions resected by endoscopic treatment, we detected APC alterations in most SNADETs from LGD to carcinoma samples." (PMID 34584977, 2021). "Methylation profiling of BRAF mutant and APC mutant cancers confirmed this model, and showed that BRAF mutant cancers had a methylation profile reminiscent of the intestinal stem cell (p)." (PMID 32384699, 2020). "Genes that are commonly hypermethylated across the four cancers in the Hippo and Wnt pathways include APC, CCND2 FZD, TCFs and WNTS (2, 3, 3A, 5A, 7A, and 9B), suggesting a link between the two pathways during oncogenesis." (PMID 33143142, 2020). "Thirteen of them were variants predicted as pathogenic by in silico tools, identified in well-known CRC predisposing genes such as APC and MUTYH, as well as variants in newly emerging cancer predisposing genes such as MSH3 and FAN1." (PMID 32635641, 2020). "Another study has identified miR-494 that leads to alteration of APC/Wnt/β-catenin signaling and promotes cancer progression." (PMID 32714979, 2020). "Mutations are mostly detected in genes encoding components of the destruction complex such as APC and AXIN, but the gene encoding β-catenin, CTNNB1, is also frequently mutated in selected cancer types." (PMID 32659938, 2020). "These cancers are extremely aggressive and the survival of patients with both BRAF and APC mutation is poor (12% 5-year survival)." (PMID 32384699, 2020). "CAC represents a type of CRC in which the IBD paved the way for the cancer, probably through mutations in K-RAS and the adenomatous polyposis coli (APC) gene." (PMID 33114313, 2020). "This attributed to role of APC that acts as a central gatekeeper protein in colorectal tumorigenesis for regulating multiple cancer pathways." (PMID 32458646, 2020). "FAP patients present with hundreds of adenomatous polyps in their colon and many of these polyps will develop into cancer, providing an early demonstration of the role of APC in cancer." (PMID 33105836, 2020).
cancer (continued). "Next, we investigated p22 activity in other cancer contexts, namely in the context of mutant intracellular components that constitutively activate the Wnt pathway i.e., truncated APC and stabilized, mutant β-catenin." (PMID 32486480, 2020). "In contrast, cell proliferation gene (BRAF), ECM-degrading gene (MMP9), cell cycle regulating and WNT signalling pathway regulator (APC) were expressed higher in the cancers of early pathological stages." (PMID 33092235, 2020). "Genetic changes in components of WNT/β-catenin signaling such as deletion of the APC gene and CTNNB1 mutations have been frequently detected in many types of human cancers." (PMID 32838807, 2020). "This will help broaden potential therapeutic targets and will help provide novel therapeutic methods for the cancers mainly driven by β-catenin-TCF/LEF complex, where APC mutation is uncommon." (PMID 32961708, 2020). "Since hereditary cancer panels are commercially produced kits, the patients included in the study were automatically evaluated for APC gene." (PMID 32283892, 2020). "This category also includes many known biomarkers for cancer diagnosis or targeted treatment, such as APC Q1291* (for COAD), EGFR L858R (for LUAD), BRAF V600E (for THCA and SKCM), DNMT3A R882H and NPM1 W288Cfs*12 (for LAML)." (PMID 31925297, 2020). "We also queried the mutational profile of TCGA-COAD and found that in high-miR-27a CRC samples there was a significant higher frequency of mutations of canonical cancer drivers in CRC, i.e. APC and K-RAS (p < 0.05; likelihood ratio test)." (PMID 32132656, 2020). "Taken together, these studies suggest that APC’s role in Wnt regulation could contribute to resistance through alterations in glutathione-dependent detoxification systems; targeting these chemoresistant mechanisms could be a therapeutic target in APC-deficient cancers." (PMID 33105836, 2020). "The APC has critical roles in the cell cycle, such as inducing progression and mitosis via breaking down various cell cycle regulators, which can lead to cancer development." (PMID 33173433, 2020). "Here we offer a perspective of APC’s dual roles—cytoskeletal hub and Wnt inhibitor—for their combined impact on gut epithelium maintenance and their dysfunction leading to cancer." (PMID 33348689, 2020). "We found that xStAx-VHLL manifested strong inhibition of Wnt signaling and sustained degradation of β-catenin in cancer cells and the intestinal organoids derived from wild-type and APC–/– mice." (PMID 32550000, 2020). "Impaired APC function leads to over-expression of β-catenin, which in turn renders cancer cells sensitive to its inhibition." (PMID 32415084, 2020). "The P103 patient, carrier of two VUS (c.4703A>G, p.(His1568Arg), in ATM and c.7667C>T, p.(Ser2556Leu), in APC), had a low-grade hormone-responsive BC and a family history for BC and other cancers." (PMID 32957588, 2020). "A recent study has revealed that MYC alterations are mutually exclusive with PIK3CA, PTEN, APC, or BRAF alterations, suggesting MYC amplification as a distinct driver mutation in the cancer genome." (PMID 32235890, 2020). "Inactivation of APC leads to increased activity of the canonical Wnt signal pathway in different cancers." (PMID 32586050, 2020). "Here, specific genes are mutated in particular types of cancer, and patients harboring germline mutations at tumor suppressor genes, such as APC and BRCA1/BRCA2, exclusively develop cancers in specific organs." (PMID 31488818, 2019). "Although APC/C serves as the E3 ligase for cyclin B1, genetic deletion of APC/C in Project Achilles showed that APC/C was an essential gene across all cancer cell lines." (PMID 30860482, 2019). "During that process, the stabilization of RAS caused by APC mutations plays important roles in the amplification of Wnt/β-catenin and RAS signaling and cancer progression via activation of the ERK and PI3K/AKT pathways downstream of RAS." (PMID 31362761, 2019).
cancer (continued). "Regarding cancer, JAK- STAT, APC, Wnt, Notch and other signaling molecules, deeply characterized in Drosophila and shared with humans, are precious for cancer drug development." (PMID 30881374, 2019). "TASIN-1 selectively targets APC truncated mutants in CRC cells and specifically kills cancer cells with APC truncations in xenografts models and in a genetically engineered CRC mouse model with minimal toxicity." (PMID 31109112, 2019). "Another one, APC gene is involved in Wnt signal pathway, which is related to the origin of cancer in humans." (PMID 31839821, 2019). "Induction of biallelic APC loss and heterozygous KRAS mutation in our mice led to the development of cancers in the proximal colon including the cecum." (PMID 31766149, 2019). "Instead, most were in moderate-penetrance genes that confer a two- to four-fold increase in cancer risk (eg, ATM and CHEK2) as well as low-penetrance mutations (eg, monoallelic MUTYH and APC I1307K)." (PMID 34322651, 2019). "Together, this study suggests that the APC/C is a potential new target in these cancer types, making it a promising target for further preclinical research." (PMID 31089208, 2019). "Other novel, highly scoring gene pair predictions that included cancer associated genes included PARP1 with PBRM1, BRCA2, ARID1A and APC as well as PIK3CA with MAP2K1, ABL1 and EGFR." (PMID 30995217, 2019). "Exercise had been shown to be a reducing agent, and even a suppressant of hypermethylation, as well as in reducing and even reversing the hypermethylation of APC and RASSF1A promoters, reducing their risk of cancer." (PMID 31772591, 2019). "The extent of phagocytosis was evaluated using flow cytometry by determining the percentage of cells staining double positive for PKH67 and anti-CD14-APC or anti-CD11b-APC over the total number of PKH67+ cancer cells." (PMID 30984171, 2019). "Blockade of STAT3 pathway represents an enticing approach because of its known capability to have an effect on inflammatory status of APC, and as shown in current study, to improve the anti-cancer immunity in NSCLC." (PMID 31511071, 2019). "Mutations in other conventional drivers (APC, KRAS, PIK3CA, ARID1A) were usually clonal within a carcinoma." (PMID 29991641, 2019). "The APC (adenomatous polyposis coli) promoter is also known to be methylated in aggressive forms of breast cancer and other cancers and serves as an inhibitor of Wnt signaling." (PMID 29691341, 2018). "APC gene is a negative regulatory element of Wnt/β-Catenin signaling pathway, which plays a critical role in cancer cell proliferation and migration, and APC down-regulation or mutation promotes cell proliferation." (PMID 30551127, 2018). "Earlier studies have also suggested that LGR5 +cells had the propensity to become cancer stem cells with APC abnormalities." (PMID 30250044, 2018). "Wnt signaling is aberrantly activated in many human cancers, including nearly all colorectal cancers, most of which are triggered by inactivation of the tumor suppressor Adenomatous polyposis coli (APC)." (PMID 29408853, 2018).
cancer (continued). "Our study has important implications for cancer therapy as recent studies have shown that inhibition of sister chromatid cohesion along with anaphase-promoting complex (APC/c) leads to the fetal mitotic arrest in several cancer cell lines." (PMID 29875144, 2018). "Several studies including our group demonstrated that SphK1 deficiency inhibits the growth of polyps induced by an adenomatous polyposis coli (APC) mutation, AOM-induced ACF formation and AOM/DSS-induced cancer development." (PMID 28583134, 2017). "APC is being inherited in an autosomal dominant pattern, which implies one copy of the altered gene would be adequate for cancer formation." (PMID 28331559, 2017). "Many genes, such as Bcl-xl, kRAS, COX, iNOS, APC, Smad3, STAT3, Ptgs2, Tnfrsf6, p16, Mlh1, Runx3, Dapk, and β-catenin are mutated in stages of carcinogenesis of the UC-associated cancer." (PMID 28621756, 2017). "From the in vitro functional analysis, insertion of mutant APC p.R805∗ led to significant increase of the viability of cancer cells." (PMID 28769798, 2017). "Accordingly, established CRCs were found to critically depend on APC mutation‐driven enhanced WNT signaling, even in the presence of additional cancer‐driving mutations." (PMID 28100566, 2017). "Genetic modulation of the pathway linking PLK1 to APC/C activation curtailed the proliferation of mutant KRAS G12D-expressing cancer cells, while ATP-competitive PLK1 inhibitors suppressed their growth as xenografts." (PMID 28807782, 2017). "Of note, in HCT116, additional mutations in the APC, FGFR3 and STK11 genes have been described in the literature but are not included in the mutations that can be detected by the hotspot cancer panel v2." (PMID 28060956, 2017). "Given the interest in the potential of targeting the APC/C in cancer, we selected APC/C cofactor Fzr from this signature to bring forward for further investigation in this study." (PMID 27655696, 2016). "In this work, PPI data and de novo motif identification based method (MEME) were used to identify such peptides in three cancer-associated hub proteins—MYC, APC and MDM2." (PMID 27218803, 2016). "Strikingly, TDO2 has more than 3-fold higher expression in the APC mutant cell lines than in the APC wide-type cell lines, indicative of the possibility of high dependence of APC mutant cancer cells on its expression." (PMID 26937901, 2016). "While many studies to date focus on blocking the activity of APC/CCdc20 as an anti-cancer strategy, we show that APC/CFzr also represents an attractive potential therapeutic target in MM." (PMID 27655696, 2016). "A significant downregulation of APC expression was observed in cancer and more advanced stage cancer samples (p ≤ 0.048)." (PMID 27898031, 2016). "Chemical inhibition of the APC/C has been proposed as a therapeutic strategy in cancer and has recently been reported to be an attractive potential therapy for MM." (PMID 27655696, 2016). "We discuss recent advances in our understanding of the involvement of APC/C and pRB in cell cycle based decisions and how these insights will be useful for development of anti-cancer and anti-viral drugs." (PMID 27402801, 2016). "We recently confirmed that cells expressing the truncated mutant APC1-1337 display a reduced rate of MT regrowth at the centrosome compared to full-length APC in cancer cell lines." (PMID 27144584, 2016).